RGS1 (regulator of G protein signaling 1)
Diseases named in the same sentence as RGS1 in open-access papers (continued):
Sharing a sentence is not in itself a finding about the gene and the disease.
lung cancer (7 papers, 2011 to 2025). A malignant neoplasm involving the lung. "With the intersection of the DEGs observed in lung cancer samples compared to normal samples, a total of 8 overlapping RGS1 + TAMs were extracted for subsequent analysis." (PMID 38653742, 2024). "This study determined regulator of G protein signalling 1 (RGS1) in peripheral blood mononuclear cells of 210 surgical nonsmall cell lung cancer (NSCLC) patients and 30 healthy controls (HCs)." (PMID 38081176, 2023). "Knockout of RGS1 notably increases the invasion and survival of helper Th1 cells and cytotoxic T lymphocytes (CTLs) in breast and lung cancer transplanted tumors, and effectively inhibits tumor growth in vivo, suggesting that RGS1 is a tumor promoter." (PMID 35879796, 2022). "For example, one study shows that RGS1 knockdown accelerates the infiltration and survival of cytotoxic T lymphocytes; meanwhile, elevated RGS1 reduces the trafficking of tumour‐specific T‐cells to tumours, which is correlated with shortened survival of breast and lung cancer patients." (PMID 38081176, 2023). "For example, overexpression of RGS1 inhibited CXCL12-mediated human plasmacytoma cell migration, and epigenetic inhibition of RGS2 has been associated with prostate cancer progression and overexpression of RGS5 on lung cancer cells." (PMID 35646090, 2022). "Regulator of G protein signalling 1 (RGS1) closely regulates malignant phenotypes and tumour immunity in several cancers, while its clinical value in nonsmall cell lung cancer (NSCLC) is by far rarely reported." (PMID 38081176, 2023).
type 1 diabetes (6 papers, 2013 to 2023). "With univariate association analysis, compared to children with type 1 diabetes only (n = 1,685), the phenotype of having multiple AIDs associated nominally with two RGS1 SNPs; rs2816316 (OR 1.88, P = 0.006) and rs2984919 (OR 1.82, P = 0.008)." (PMID 29182645, 2017).
cervical cancer (5 papers, 2020 to 2024). A primary or metastatic malignant neoplasm involving the cervix. "A study had shown that RGS1 is highly expressed in advanced cervical cancer and is associated with cancer progression." (PMID 33271935, 2020). "Using cervical cancer cell lines, we demonstrated that knockdown of RGS1 inhibited the proliferation, invasion, migration and promoted apoptosis of cancer cells." (PMID 35879796, 2022). "Our results demonstrated the potential of RGS1 as a target for cervical cancer immunotherapy and added new possibilities for immunotherapy in patients with cervical cancer." (PMID 35879796, 2022). "In vivo experiments with a focus on nude mice tumorigenesis revealed that, RGS1 knockdown notably inhibited the growth of cervical cancer transplanted tumors." (PMID 35879796, 2022). "Transwell and flow cytometry results showed that compared with the sh-NC group, the invasion and migration of cervical cancer cells were decreased, and the apoptosis rate was increased in the sh-RGS1 group." (PMID 35879796, 2022). "In cervical cancer cell lines, knockdown of RGS1 can inhibited cell proliferation, migration, invasion, and tumor growth in nude mice and promoted apoptosis." (PMID 35879796, 2022). "RGS1 had higher expression in cervical cancer tissues than normal tissues, especially in HPV-E6 positive cancer tissues." (PMID 35879796, 2022). "It was proved that RGS1 was highly expressed in cervical cancer tissues, especially in HPV-E6 positive cancer tissues and accelerated the malignant development of cervical cancer in vivo and in vitro experiments." (PMID 35879796, 2022). "We found that the quantity of RGS1 mRNA expression in cervical carcinoma tissues was higher than normal cervical tissues, and the quantity of RGS1 mRNA expression in squamous cell carcinoma tissues was increased compared with adenocarcinoma carcinoma tissues." (PMID 35879796, 2022). "RGS1, as an oncogenic gene of cervical cancer, affects the immune microenvironment of patients with cervical cancer and may be a target of immunotherapy." (PMID 35879796, 2022). "This study once again verified the tumor-promoting effect of RGS1 in cervical cancer." (PMID 35879796, 2022). "Finally, we analyzed the expression and biological function of RGS1 in cervical cancer by experiments." (PMID 35879796, 2022). "Similarly, compared with normal cervical tissues, the quantity of RGS1 protein expression was increased in cervical carcinoma tissues and the quantity of RGS1 protein expression in squamous cell carcinoma tissues was higher than adenocarcinoma carcinoma tissues." (PMID 35879796, 2022). "In this study the core gene, RGS1, which affects immune status and the FIGO stage of cervical cancer patients was identified by WGCNA analysis and differential analysis using TCGA database." (PMID 35879796, 2022). "Regulator of G protein signalling 1 (RGS1), belonging to the R4 subfamily of RGS proteins, is an inhibitor of G protein‐coupled receptors (GPCRs) that closely involves in malignant phenotypes of several cancers, such as osteosarcoma and cervical cancer." (PMID 38081176, 2023). "RGS1 mediates T cell retention, leading to T cell depletion, which may be a target for improved CAR-T therapy in cervical cancer." (PMID 35879796, 2022). "We investigated the effect of RGS1 on the clinical relevance of CESC patients, and experimentally verified the differences in RGS1 expression between cervical cancer patient tissues and normal cervical tissues, the role of RGS1 in cell function, and the effect on tumor growth in tumor-bearing mice." (PMID 35879796, 2022).
diffuse large B-cell lymphoma (4 papers, 2020 to 2023). "Among the different gene candidates, RGS1 was selected because a reliable primary antibody for immunohistochemistry was available, and we previously showed that high RGS1 protein expression correlated with poor prognosis in diffuse large b-cell lymphoma." (PMID 35052318, 2022).
colon cancer (3 papers, 2014 to 2025). "Moreover, the normal group of RGS1 in pre-existing tumors and normal tissue pairs were expressed higher than the tumor group in some tumors (e.g., bladder metastatic cell carcinoma, colon cancer, and rectal adenocarcinoma)." (PMID 37735297, 2024). "First, the role of RGS1 in colon cancer–associated phenotypes is not well documented." (PMID 40754247, 2025). "In colon tumor tissue, similar gene expression changes were found for CYR61, RGS1, DUSP1, DUOX2, and SLC6A14, although the log-fold change was generally lower compared to normal tissue." (PMID 25526028, 2014). "This distinction highlights RGS1’s suitability as a negative control for exploring the relationship between RGS proteins and cancer-associated signaling events in colon cancer cells." (PMID 40754247, 2025).
glioblastoma multiforme (3 papers, 2021 to 2024). "When the gene expression was ranked in order among the tumors, the results showed that glioblastoma multiforme had much greater levels of RGS1 expression than normal tissues, with ccRCC coming in second." (PMID 37735297, 2024).
inflammatory bowel disease (3 papers, 2016 to 2025). A spectrum of small and large bowel inflammatory diseases of unknown etiology. "In Gnai2−/− mice developing spontaneous inflammatory bowel disease, gut-derived T cells from Rgs1−/− mice displayed increased chemotaxis to CXCL12, suggesting that the balance between expression of Gαi2 and RGS1 in gut T cells may control their retention within the gastrointestinal mucosa." (PMID 27804980, 2016).
lymphoma (3 papers, 2012 to 2023). A malignant (clonal) proliferation of B- lymphocytes or T- lymphocytes which involves the lymph nodes, bone marrow and/or extranodal sites. "Interestingly, the lymphoma cells were positive for HLA-DP-DR, IL-10, and RGS1, which are markers associated with poor prognosis in DLBCL." (PMID 36975733, 2023). "RGS1 is a member of the regulator of G protein-signaling family, expressed in GC B cells and lymphoma cell lines in which it desensitizes cells to chemoattractant, localizing cells to the lymph node." (PMID 32679859, 2020).
Obesity (3 papers, 2018 to 2024). Accumulation of substantial excess body fat. "In our previous study, we reported that 14 adipocyte genes (Ccl7, Emr1, Evi2a, Gusb, H2-DMb2, Lcp1, LOC100041137, Ly9, Ptpre, Rgs1, sc1000528.1_16, Sirpa, Sfrp5, and Acacb) were associated with both advanced age and diet-induced obesity." (PMID 30282902, 2018). "Differential gene expression revealed that genes associated with innate immune responses (LYZ), antigen processing and presentation (HLA-DRB1, HLA-DRB5, IFI30), as well as cell signaling and migration (VIM, RGS1, NCF) were upregulated in the HBC subset with pregravid obesity." (PMID 39872537, 2024).
osteosarcoma (3 papers, 2022 to 2023). A usually aggressive malignant bone-forming mesenchymal neoplasm, predominantly affecting adolescents and young adults. "For instance, one previous study discloses that RGS1 facilitates cell proliferation, migration and invasion but retards cell apoptosis of osteosarcoma cells." (PMID 38081176, 2023).
ovarian carcinoma (3 papers, 2013 to 2023). A malignant neoplasm originating from the surface ovarian epithelium. "Previous studies have identified the increased blood RGS1 expression in many solid tumours, including hepatocellular carcinoma, renal cell carcinoma and ovarian cancer." (PMID 38081176, 2023). "Of interest to clear cell ovarian cancer, the gene product of RGS1, RGS1 or BL34, is a member of the RGS protein family whose members are involved in regulation of G-protein signaling." (PMID 23382860, 2013). "Based on these prior studies, it is tempting to speculate that genetically determined RGS1 levels may regulate Treg infiltration into clear cell ovarian cancers and thus contribute to outcome." (PMID 23382860, 2013). "Concerning the prognostic value of RGS1, one previous study discloses that increased tumour RGS1 expression is related to poor DFS in ovarian cancer patients." (PMID 38081176, 2023). "We found that the expression intensity and quantity of PI3, RGS1, PTGER3 and CCDC80 in ovarian cancer tissue was higher than that in normal ovarian tissue." (PMID 33271935, 2020).
periodontitis (3 papers, 2015 to 2026). An acute or chronic inflammatory process that affects the tissues that surround and support the teeth. "Machine learning models, combined with Gene Set Variation Analysis (GSVA), identified five key genes (RGS1, ACAT2, KDR, TUBB2A, TDO2) linked to periodontitis." (PMID 39935835, 2025).
asthma (2 papers, 2022 to 2023). "Interestingly, a small subpopulation of mast cells comprised mostly of cells from asthma horses and displayed higher expression of e.g., the asthma associated genes FKBP5, RGS1 and LTC4S, suggesting a role in inflammation." (PMID 37758813, 2023). "To date, no studies have reported on the relationship between CD3D, CD3G, RGS1, HLA-DMB, GBP4, GBP5, and asthma." (PMID 36118895, 2022).
Autoimmunity (2 papers, 2022). The occurrence of an immune reaction against the organism's own cells or tissues. "The next three upregulated genes in treated individuals were DNAJB1, which is a part of the HSP40 complex that has been shown to play a role in anti-inflammatory processes in autoimmunity; and RGS1 and SOD1, which are important for antiviral immune responses." (PMID 36175869, 2022).
bladder cancer (2 papers, 2021 to 2024). "Previous studies had explored the associations between RGS family members and bladder cancer risk, including RGS1, RGS2, RGS4, RGS5, RGS6, and RGS20." (PMID 34482807, 2021). "Of course, RGS1 is down-regulated in some tumors such as bladder cancer, rectum adenocarcinoma, and thyroid carcinoma (from TCGA databank), which can interfere with its use as a biomarker for the diagnosis of OTB." (PMID 39123125, 2024).
Burkitt lymphoma (2 papers, 2015). A rare form of malignant mature B-cell non-Hodgkin lymphoma. "RGS1 has been found to be up-regulated in vitro in C57Bl/6 mouse ischemic retinas compared with non-ischemic retinas and has been shown to be inducible in response to hypoxia e.g. in Burkitt`s lymphoma cell-lines." (PMID 26222051, 2015). "Interestingly, knockdown of RGS1 in HS-sultan Burkitt's lymphoma cells enhances migration only marginally." (PMID 25897806, 2015).
colitis (2 papers, 2013 to 2015). Inflammation of the colon. "In addition, when Rgs1−/− and wild-type T cells are transferred in the inflammatory colitis model in Rag2-deficient mice, wild-type mice were more susceptible to colitis, presumably through RGS1 repressing T-cell egress from the gut14 associating RGS1 in having a key role in leukocyte accumulation." (PMID 25782711, 2015). "Furthermore, when Rgs1−/− and wild type T-lymphocytes were transferred in the colitis model in Rag2 deficient mice which lack mature lymphocytes, Rgs1 deficiency showed a protective phenotype indicating RGS1 in having a potential role in T-lymphocyte retention in the gut." (PMID 23690662, 2013).
COVID-19 (2 papers, 2023). A disease caused by infection with severe acute respiratory syndrome coronavirus 2. "We then compared CD3+ cells isolated from COVID-19-infected subjects vs. healthy controls and found increased expression of activation markers including CD69, CD83, ICOS, RGS1 as well as other stress related genes including HIF1A, ATF4, NFKB1, and PR1." (PMID 36881624, 2023). "Furthermore, marker genes for the MT1G-high non-alveolar macrophage Cluster 3 and the RGS1-high Cluster 6 matched those identified in BAL fluid of healthy controls and patients with COVID-19, while the SERPINB2-high Cluster 13 matched marker genes from BAL cells obtained in healthy and COPD lungs." (PMID 38132091, 2023).
esophageal cancer (2 papers, 2021 to 2025). A primary or metastatic malignant neoplasm involving the esophagus. "For example, in esophageal cancer, microRNA-mediated downregulation of RGS1 has been associated with increased cell proliferation, migration, and the expression of cancer-related genes." (PMID 40754247, 2025).
Hypertension (2 papers, 2018 to 2023). The presence of chronic increased pressure in the systemic arterial system. "We used Rgs1−/− mice on an ApoE−/− background, as hyperlipidemia is a common co-morbidity with hypertension." (PMID 29654907, 2018). "Rgs1 also resides in the same locus of chromosome 1q, which harbours multiple susceptibility genes that affect blood pressure levels, indicating potential SNPs in Rgs1 could also affect hypertension in humans." (PMID 29654907, 2018). "Specifically, pharmacological agents that up-regulate RGS1 expression or activity in the vessel wall may augment the action of vasodilatory agonists and provide a novel means of treating hypertension." (PMID 29654907, 2018). "Furthermore, genetic impairment of Rgs1 therefore may contribute to the development of hypertension." (PMID 29654907, 2018). "However the precise role of RGS1 in hypertension and vascular-derived cells remains unknown." (PMID 29654907, 2018).
plasmacytoma (2 papers, 2015 to 2022). Plasmacytoma is a localized mass of neoplastic monoclonal plasma cells that represents approximately 5% of all plasma cell neoplasms. "The present study examines the functional role of RGS1 in regulating the CXCL12-mediated migration of RPMI 8226 plasmacytoma cells and plasmablasts." (PMID 25897806, 2015). "Here, we show that RGS1 controls the chemotactic migration of RPMI 8226 human plasmacytoma cells and human plasmablasts." (PMID 25897806, 2015). "In this paper, we investigated the role of RGS1 in human plasmacytoma and plasmablast." (PMID 25897806, 2015). "We found that augmented expression of RGS1 by lipopolysaccharide (LPS) suppressed the CXCL12-mediated migration and AKT activation in RPMI 8226 plasmacytoma cell line and plasmablasts generated from germinal center B (GC-B) cells." (PMID 25897806, 2015). "However, up to date, function of RGS1 in migration of human plasma cell or plasmacytoma has not been investigated." (PMID 25897806, 2015).
psoriasis (2 papers, 2011 to 2026). An autoimmune condition characterized by red, well-delineated plaques with silvery scales that are usually on the extensor surfaces and scalp. "For example, rs2816316 on near RGS1 exhibits evidence of association to MS; rs2542151 and rs1893217 on near PTPN2 has modest association to psoriasis." (PMID 21852963, 2011).
Sepsis (2 papers, 2015 to 2025). Sepsis is defined as life-threatening organ dysfunction caused by a dysregulated host response to infection. "In contrast, sepsis Treg cells displayed four upregulated genes (RGS1, HLA-DPA1, BTG1, and GAPDH; 1.25, 1.02, 0.44, and 0.43log2FC, respectively)." (PMID 41208955, 2025). "In sepsis RGS1, along with IRF4 and GAPDH, were highly upregulated across all B cell populations compared to control cells." (PMID 41208955, 2025). "Furthermore, RGS1, CCL3, and SOCS1 were connected to sepsis in animal studies, while for CTSD increased expression levels were observed in mice with induced septic shock." (PMID 25814982, 2015).
AIDS (1 paper, 2017). A syndrome resulting from the acquired deficiency of cellular immunity caused by the human immunodeficiency virus (HIV). "The direction of effect for RGS1 association was the same as in the univariate analyses (minor allele increases risk for other AIDs)." (PMID 29182645, 2017). "The specific SNPs associated with having multiple AIDs were neuropilin 1 (NRP1, rs2666236), RGS1 (rs2816316), CD69 (rs4763879), and FUT2 (601338)." (PMID 29182645, 2017).
Alzheimer disease (1 paper, 2020). A progressive, neurodegenerative disease characterized by loss of function and death of nerve cells in several areas of the brain leading to loss of cognitive function such as memory and language. "RGS1 was upregulated in both PBMC and brain samples from Alzheimer’s disease patients." (PMID 33302351, 2020).
aneurysm (1 paper, 2015). Bulging or ballooning in an area of an artery secondary to arterial wall weakening. "To specifically address the role of Rgs1 in the accumulation or emigration of monocyte-derived cells in the aortic wall during aneurysm development, we used a pulse-chase approach to track bead-labelled monocytes in aortas following Ang II infusion." (PMID 25782711, 2015). "Because of the associations between aortic atherosclerosis, vascular inflammation and the pathogenesis of AAA15, we next sought to determine whether Rgs1 is related to human aneurysms." (PMID 25782711, 2015). "Furthermore, between days 3 and 5 of Ang II infusion, two out of six ApoE−/− mice died from aneurysm rupture, but no deaths occurred in Rgs1−/−ApoE−/− mice, indicating that Rgs1 deficiency confers protection from Ang II-induced aortic aneurysm rupture." (PMID 25782711, 2015).
aortic aneurysm (1 paper, 2015). A ruptured aneurysm located in the wall of the proximal portion of the descending aorta proceeding from the arch of the aorta. "Although the findings of this study implicate RGS1 in the formation of fatty-streak lesions and aortic aneurysm rupture, identification of the downstream signalling pathways by which macrophages accumulate remains to be determined." (PMID 25782711, 2015). "In early atherosclerotic lesions, Rgs1 regulates macrophage accumulation and is required for the formation and rupture of Angiotensin II-induced aortic aneurysms, through effects on leukocyte retention." (PMID 25782711, 2015). "Together these data suggest that RGS1 is a mediator of inflammatory monocyte accumulation in aortic aneurysms." (PMID 25782711, 2015). "Here we show that Rgs1 is upregulated in atherosclerotic plaque and aortic aneurysms." (PMID 25782711, 2015). "Taken together, these results suggest that Rgs1 expression in bone marrow-derived cells, rather than vascular cells, is crucial for aortic aneurysm rupture." (PMID 25782711, 2015).